MTOR (mechanistic target of rapamycin kinase)
Diseases named in the same sentence as MTOR in open-access papers (continued):
Sharing a sentence is not in itself a finding about the gene and the disease.
tumor (continued). "Inhibition of mTOR function can deactivate the PI3K/Akt/mTOR pathway and induce autophagy in tumor cells." (PMID 39648951, 2025). "Apigenin has affected the PI3K/AKT/mTOR signaling pathway by promoting ER‐α/ER‐β expression, slowing tumor development by histamine." (PMID 40634118, 2025). "Oncogenic alterations within the RAS/RAF/MEK/ERK cascade and FGFR fusions converge on the PI3K/Akt/mTOR axis, resulting in sustained pathway activation that promotes uncontrolled proliferation, tumor progression, and metastatic dissemination." (PMID 41155242, 2025). "The results demonstrated a reduction in the levels of mTOR phosphorylation, Similarly, in the xenograft tumor samples, the p-mTOR level was found to be reduced in the sh-DUSP6 group." (PMID 40936711, 2025). "Our findings demonstrate that Sesn2 functions as an oncogene in OSCC, promoting tumor progression by modulating the PI3K/AKT/mTOR and MAPK signaling pathways, suggesting its potential as a therapeutic target for OSCC." (PMID 41614860, 2025). "mTOR inhibitors have emerged as promising therapeutic candidates for restoring apoptotic sensitivity and suppressing tumor growth, particularly in CRC." (PMID 40702333, 2025). "The mTOR signaling pathway has been extensively investigated for its role in signaling downstream of tumor cell oncogenes such as PIK3CA and KRAS." (PMID 40821795, 2025). "A recent report describes a novel eIF2E/MTOR-independent mode of cap-dependent translational initiation that affects tumor metastasis and anoikis." (PMID 41239272, 2025). "GPNMB, which is consistently expressed in TSC/mTOR altered tumours, was positive in both components." (PMID 40590246, 2025). "Potential signaling mechanisms of MRPL13 involve PI3K, AKT, and mTOR as demonstrated in the regulation of BRCA tumor cell proliferation and migration." (PMID 39913623, 2025). "This review seeks to tease out the complex interactions between these genes, throwing light on key signaling pathways such as MAPK/ERK, PI3K/AKT/mTOR, and Wnt/β-catenin, all of which play a role in the progression of the tumor." (PMID 40227591, 2025). "A study analyzing 130 paired tumor/normal bone tissue samples demonstrated significant downregulation of miR-99a in OS tissues, which inversely correlated with mTOR mRNA overexpression." (PMID 40979744, 2025). "Pterostilbene significantly suppressed many important pathways central to tumor progression, including oxidative phosphorylation, glycolysis, hypoxia, and mTOR signaling." (PMID 40227411, 2025). "AI-HOPE-PI3K was further applied to examine tumor mutational burden (TMB) and its relationship with MTOR mutation status and survival in FOLFIRI-treated CRC patients." (PMID 40650262, 2025). "These strategies aim to modulate tumor growth and enhance immune responses by influencing signaling pathways that intersect with mTOR signaling." (PMID 41469379, 2025). "This aligns with established mechanisms through which EAAs promote tumor progression via the PI3K/Akt/mTOR pathway." (PMID 41568043, 2025). "Remarkably, these alterations are fully reversed within hours of acute treatment with the ATP-competitive mTORC1/2 kinase inhibitor AZD8055, demonstrating the direct and dynamic role of mTOR in mediating the tumor-induced alterations to peritumoral neurons." (PMID 41301687, 2025). "Recent research has indicated that DEFB1 participates in the RTK/PI3K/AKT/mTOR pathway, potentially influencing the adaptability and invasion of tumor cells within the TME." (PMID 40881700, 2025). "Second, RT induces transient expression of MHC/peptide complexes on tumor stromal cells by activating the mTOR pathway, these newly generated peptides bind to MHC I and are presented on the surface of tumor cells, significantly enhancing their immunogenicity." (PMID 40900811, 2025).
tumor (continued). "Abnormal activation of the PI3K/AKT/mTOR pathway can inhibit tumor cell apoptosis, promote tumor cell growth and proliferation, facilitate tumor cell angiogenesis and metabolism, participate in tumor cell invasion and metastasis." (PMID 40013141, 2025). "This facilitates enhanced glucose uptake and accelerates tumor cell metabolism, potentially contributing to the hyperglycemia, ketosis, and insulin dependency observed in some patients receiving mTOR-targeted therapies." (PMID 40989687, 2025). "The mammalian target of rapamycin (mTOR) as TFE3 upstream regulator is targetable in some TFE3 rearranged tumor, like Xp11-RCC and ASPS." (PMID 39917171, 2025). "In this study, we observed that the recombinant oncolytic adenovirus delivering apoptin induced apoptosis in MCF-7 tumour cells, accompanied by significant alterations in key proteins of the mTOR/S6K signalling pathway." (PMID 40453070, 2025). "Albumin-bound sirolimus is a novel mTOR inhibitor that improves drug delivery efficiency and tumor targeting via an albumin carrier." (PMID 40989692, 2025). "PTEN is a tumor suppression gene and loss of its function results in activation of the PI3K/AKT/mTOR pathway, which has been found to be associated with adverse oncological outcomes in patients with PCa." (PMID 40104315, 2025). "When tumor epithelial cells are deprived of amino acids, repression of mTOR rearranges cellular metabolism to utilize amino acids derived from ECM protein degradation, to the benefit of nutrient-starved cells." (PMID 40519272, 2025). "The activation of PI3K/AKT/mTOR pathway is known to be closely related to PD-L1 expression and can iimpact the tumor immune microenvironment." (PMID 40149335, 2025). "It exhibits strong anticancer effects through ferroptosis via IGF2BP3/GPX4 pathways, induces mitochondrial apoptosis, and targets NF-κB, ERK, and PI3K/Akt/mTOR to suppress tumor progression." (PMID 41465430, 2025). "TAMs increase the secretion of chemokine CXCL5, which not only recruits monocytes but also activates the PI3K/AKT/mTOR pathway in tumor cells, mediating therapeutic resistance and tumor cell survival." (PMID 39941714, 2025). "They suggested that IST holds potential as an off-label cancer treatment, promoting an anti-tumor response through the production of pro-inflammatory cytokines and inhibition of the AKT/mTOR tumor growth pathway." (PMID 40003608, 2025). "Metformin, a first-line therapy for T2DM, improves insulin sensitivity and has demonstrated potential anti-tumor activity in experimental models by inhibiting the mammalian target of rapamycin (mTOR) signaling pathway." (PMID 40764810, 2025). "Loss of NF2 function can activate mTORC1 through integrin signaling, promoting tumor cell proliferation and PM cells with NF2 loss exhibit sensitivity to mTOR inhibitors, such as rapamycin." (PMID 40904706, 2025). "As is well known, triggering tumor cell apoptosis is related to various signaling pathways (PI3K/AKT/mTOR, MAPK, JAK/STAT3, and NF-κB, etc.)." (PMID 41220717, 2025). "We found modulations in core cellular processes involved in tumor progression, such as anabolism (ElF2 and mTOR signaling) and metabolic control (Sirtuin signaling), in GBM cells exposed to MSC or MSCMel." (PMID 40083939, 2025). "Everolimus, a mammalian target of rapamycin (mTOR) inhibitor, achieves triple anti-tumor effects by blocking the PI3K-AKT-mTOR signaling pathway: inhibiting tumor cell growth, reducing tumor cell nutrient metabolism, and affecting tumor angiogenesis." (PMID 41487525, 2025). "In mUC, upregulation of the PI3K/AKT/mTOR pathway correlates with increased EV resistance and enhanced tumor cell survival." (PMID 41409251, 2025). "PD-L1 is a crucial regulator of tumor glucose metabolism, as demonstrated by studies indicating that inhibition of PD-L1 disrupts glycolysis by suppressing mTOR activity and decreasing glycolytic enzyme expression." (PMID 39858015, 2025).
tumor (continued). "Akt phosphorylates pro-apoptotic proteins to enhance the anti-apoptotic function of Bcl-2/Bcl-xl, while mTOR activation accelerates protein synthesis to fuel tumor expansion." (PMID 40363681, 2025). "One prominent mechanism involves the activation of PI3K/AKT/mTOR pathway which promotes tumor cell survival and proliferation." (PMID 41409251, 2025). "Transcriptomic profiling following MITF silencing further demonstrated enrichment of differentially expressed genes in PI3K/ mTOR signaling, with downstream effects on tumor growth and autophagy." (PMID 41168571, 2025). "We showed that CD-3 activates PP2A by inhibiting CIP2A and produces tumor growth inhibitory effects by promoting dephosphorylation of oncogenic AKT/mTOR signaling proteins in SCSC cells and xenograft tumors in a PP2A-dependent manner." (PMID 39850502, 2025). "The signaling pathway comprising phosphoinositide 3‐kinase (PI3K), protein kinase B (AKT), and mammalian target of rapamycin (mTOR) is essential for tumor cell communication, influencing cell growth, division, and maintenance." (PMID 39802639, 2025). "Studies have found that mTOR inhibitors can inhibit the growth of tumor regions rich in nutrients, but, in the central regions that rely on the YY1–FGD6 axis, the inhibitory function of mTOR inhibitors on cell growth is weakened." (PMID 40867514, 2025). "The biological functions of tumor cells are affected when mTOR signaling is activated, such as apoptosis and autophagy." (PMID 40123978, 2025). "In OSCC, pharmacologic or genetic inhibition of the PI3K/AKT/mTOR cascade effectively suppresses tumor-cell proliferation, invasion, and metastatic dissemination." (PMID 41614860, 2025). "We identify the previously underexplored ECM protein, MFAP4, as a key tumor suppressor in TNBC that functions by restraining the PI3K/AKT/mTOR pathway, a cornerstone of TNBC malignancy." (PMID 41451212, 2025). "Alteration of the PI3K/AKT/mTOR signaling pathway also contributes to tumor cell survival, proliferation, angiogenesis, metastasis, EMT, and chemotherapy resistance." (PMID 40863244, 2025). "Other gene mutations are also involved in the formation of RCC: PBRM1 is potentially associated with tumor immune escape; BAP1 and SETD2 participate in DNA repair regulation; and MTOR regulates the critical PI3K/AKT/mTOR signaling pathway." (PMID 41405787, 2025). "The PI3K/AKT/mTOR signaling pathway is one of the most common tumor-related signaling pathways and also plays a key role in the progression of RCC." (PMID 41181710, 2025). "Chitosan oligosaccharide appeared to inhibit the nuclear factor–κB (NF-κB) signaling and mammalian target of rapamycin (mTOR) signaling typically involved in the early stages of tumor development." (PMID 39530850, 2025). "Tumor gene expression analysis for this patient demonstrated an over‐activation of PI3K/AKT/mTOR signaling." (PMID 39876058, 2025). "Regulates lipid deposition, β-catenin activation, and interacts with Wnt and mTOR pathways in tumor growth." (PMID 40370434, 2025). "This interaction can transduce signals that inhibit the PI3K/AKT/mTOR cascade or compete with other tumor-promoting ligands for receptor binding." (PMID 41451212, 2025). "Nevertheless, targeting signaling pathways activated in canine and human MM, such as Ras/MAPK and PI3K/AKT/mTOR, remains a viable option due to their frequent activation and vital role in supporting tumor growth." (PMID 40568110, 2025). "Emerging evidence suggests that inhibition of the PI3K/mTOR pathway enhances the efficacy of immunotherapy through multiple mechanisms, including modulation of the tumor microenvironment, epigenetic reprogramming, and direct effects on immune cell function." (PMID 40386392, 2025). "miR-185 exerts its tumor-suppressive function by targeting the PI3K/AKT/mTOR and Wnt/β-catenin pathways, both of which are crucial for ES cell survival and metastasis." (PMID 40429954, 2025).
tumor (continued). "These alterations trigger the PI3K/AKT/mTOR signaling pathway, increasing glycolysis and providing the energy necessary for tumor cell survival and growth." (PMID 40303296, 2025). "circZKSCAN1 encodes circZKSaa, which plays a tumor-inhibiting role in the PI3K/AKT/mTOR pathway and sensitizes HCC cells to the first-line drug sorafenib by mediating the ubiquitination of mTOR to inhibit HCC development." (PMID 40034125, 2025). "The mechanism for this involves the suppression of the KRAS downstream pathway PI3K/AKT/mTOR by ART to suppress tumor cell proliferation." (PMID 40142963, 2025). "The PI3K/mTOR pathway is a signal transduction pathway involved in cell growth and proliferation and is another critical target for tumor-directed therapy in pediatric CNS tumors." (PMID 40094009, 2025). "The AKT/mTOR signaling pathway acts as an intermediate junction in tumor cells and can be regulated by the proto-oncogenes Ras or Src, as well as by Myc activity." (PMID 41392241, 2025). "In particular, hyperactivation of PI3K/Akt/mTOR contributes to the progression of numerous solid tumors, and flavonoids can inhibit critical kinases within this pathway, thus curtailing tumor growth and inducing apoptosis." (PMID 40084006, 2025). "NR6A1 acts as a repressor of mTOR activity: low levels of NR6A1 contribute to mTOR activation, favoring the transcription of pro-tumor genes related to lipogenesis, angiogenesis, and NFkB signaling." (PMID 41550951, 2025). "The PI3K/AKT/mTOR signaling pathway is a key upstream signaling pathway for cell cycle progression, and its abnormal activation can affect tumor progression, metabolism, invasiveness, and drug responsiveness." (PMID 39910045, 2025). "Studies have demonstrated that liraglutide significantly impairs colorectal cancer cell migration, invasion, and proliferation by inhibiting the PI3K/Akt/mTOR signaling pathway, while concurrently promoting tumor cell apoptosis." (PMID 40140925, 2025). "Similar to PD-L1, PD-1 also can be palmitoylated by ZDHHC9, which promotes the trafficking of PD-1 to the recycling endosome and prevents its lysosome-dependent degradation, thereby activating mTOR signaling and tumor cell proliferation." (PMID 40814339, 2025). "The combination therapy was achieved through remodeling tumor metabolism and tumor immune microenvironment by modulation of the mTOR (mammalian target of rapamycin) pathway." (PMID 40565632, 2025). "In PM, overactivation of the PI3K/Akt/mTOR signaling pathway is considered a major mechanism driving tumor cell proliferation and resistance to apoptosis." (PMID 40904706, 2025). "By suppressing PI3K-mediated PIP3 generation, these agents attenuate downstream Akt/mTOR signaling, thereby disrupting tumor cell proliferation, survival, and metabolic reprogramming." (PMID 40266213, 2025). "The phosphoinositide 3-kinase (PI3K)/AKT/mammalian target of rapamycin (mTOR) axis orchestrates key processes in cellular metabolism, growth, and survival, and constitutes a central oncogenic driver across multiple tumor types." (PMID 41228293, 2025). "In contrast, acquired resistance mechanisms include the activation of compensatory pathways such as FGFR1, MAPK, PI3K/AKT/mTOR, Myc, Hippo, tumor metabolism, and alterations in the TME." (PMID 39955556, 2025). "Taken together these data show that sapanisertib plus serabelisib, with the optional addition of ISD, represents a comprehensive multi-nodal approach for the effective inhibition of PI3K/AKT/mTOR signalling in tumours in vivo." (PMID 40360883, 2025). "This prevents ERα-mediated transcription of estrogen-responsive genes, which inhibits tumor cell proliferation by suppressing the PI3K/Akt/mTOR signaling pathway." (PMID 41301038, 2025). "As a classic pathway in tumor signal transduction research, PI3Kα/Akt/mTOR plays a key regulatory role in carcinogenesis." (PMID 40723456, 2025).
tumor (continued). "Targeting QSOX2 with Ebselen, in combination with mTOR inhibitor Rapamycin and chemotherapy, effectively downregulates c‐Myc expression and induces tumor dormancy in a mouse xenograft model." (PMID 40433832, 2025). "During the process of tumor proliferation and migration, the PI3K/AKT/mTOR signaling pathway is often activated, while the tumor suppressor gene PTEN can inhibit the activation of the PI3K/AKT/mTOR pathway under physiological conditions." (PMID 41394131, 2025). "Metformin-mediated AMPK activation can induce PD-L1 degradation and interfere with anabolic processes in tumor cells via inhibiting mTOR." (PMID 39776799, 2025). "By reprogramming cellular metabolism, the PI3K/AKT/mTOR pathway supports the growth and survival of highly proliferative, poorly differentiated tumor cells." (PMID 40072110, 2025). "Silencing RRM2 inhibits PC cell proliferation and tumor growth by inactivating the PI3K/AKT/mTOR pathway, leading to cell cycle arrest and/or apoptosis." (PMID 41200180, 2025). "Sasanquasaponin III, an important constituent of Theaceae, induces autophagy activation through the AKT/mTOR/p70S6K pathway and inhibits tumor metastasis in melanoma cells." (PMID 40331942, 2025). "We utilized clinically relevant mTOR inhibitors capable of mTORC1-selective or dual mTORC1/2 blockade to elucidate the important role of mTORC2 signaling in tumor cell survival and dissected their effects in various TNBC cells harboring RICTOR amplification." (PMID 40019775, 2025). "It was also shown that RTK-driven tumour cells with elevated mTOR signalling and increased basal rates of nascent protein synthesis were more sensitive to eFT226." (PMID 40805230, 2025). "In OC, hypoxia has been demonstrated to stimulate the production of miR‐9‐5p, accelerating migration, invasion, and tumor proliferation through the PI3K/AKT/mTOR/GSK3β, thereby recognizing miR‐9 as a prospective oncogenic driver and therapeutic target." (PMID 40740483, 2025). "Thioridazine further modulates pathways like PI3K/Akt/mTOR, suppressing tumor growth by downregulating cyclins and upregulating p21 and p27." (PMID 40718442, 2025). "Hyperactivation of the PI3K/Akt/mTOR pathway is frequently observed in various cancer types, where it contributes to tumor cell survival, proliferation, and growth." (PMID 40725182, 2025). "This translocation further regulates the AMPK/mTOR pathway and inhibits the autophagy of tumor cells." (PMID 41360767, 2025). "Given the complex biology of mTOR signaling, attention has shifted toward evaluating the tumor microenvironment (TME) and its components." (PMID 41322031, 2025). "Mechanistically, dual blockade of G1/S transition (via CDK4/6 inhibition) and mTOR-mediated metabolic support synergistically disrupted tumor proliferation." (PMID 40979744, 2025). "Taken together, these results strongly indicated that SESN3 plays a novel tumor-suppressor role in T-ALL possibly through its inhibition of both mTOR signaling and autophagy activity." (PMID 41275290, 2025). "Hyperactivation of mTOR promotes tumor growth, survival, and metastasis by stimulating cell proliferation, angiogenesis, and resistance to apoptosis." (PMID 39941728, 2025). "The AMPK pathway counteracts mTOR signaling, with AMPK activation in tumor-associated DCs typically inducing tolerogenic properties characterized by improved mitochondrial function, increased FAO and OXPHOS, and diminished CD80/CD86 expression." (PMID 40924040, 2025). "Our study illustrates that combining Everolimus with NDV and Beclin-1, which not only inhibits mTOR but also enhances autophagy, leading to increased tumor cell death." (PMID 40403026, 2025).